TCL1B (TCL1 family AKT coactivator B)
Description:
Enhances the phosphorylation and activation of AKT1 and AKT2.
Synonyms: TML1; SYN-1
Tractability: PROTAC: ubiquitination databases record sites on it.
Gene: Protein-coding gene on chromosome 14 (95,686,397 to 95,692,638, forward strand). Ensembl gene ENSG00000213231.
Subcellular location (Human Protein Atlas): Cytosol
Gene Ontology:
Molecular function: protein binding; protein kinase binding; protein serine/threonine kinase activator activity
Biological process: intracellular signal transduction
Genetic constraint (gnomAD): Loss-of-function variants: 12 observed, 15.91 expected, observed/expected ratio (o/e) 0.75, 90% interval 0.48 to 1.22. The upper end of that interval is the gene's LOEUF score, 1.22, which puts it in group 5 of 6, group 1 being the genes least tolerant of losing a copy. Missense variants: 162 observed, 166.11 expected, observed/expected ratio (o/e) 0.98, 90% interval 0.86 to 1.11. Synonymous variants: 75 observed, 64.55 expected, observed/expected ratio (o/e) 1.16, 90% interval 0.96 to 1.41.
Homologues: Orthologues: chimpanzee TCL1B (99% identical), macaque TCL1B (91% identical), dog TCL1B (57% identical), pig TCL1B (55% identical), mouse Tcl1b4 (33% identical), mouse Tcl1b3 (30% identical), mouse Tcl1b1 (30% identical), mouse Tcl1b2 (27% identical), mouse Tcl1b5 (27% identical). Paralogues in human: MTCP1 (30% identical), TCL1A (28% identical).
Diseases named in the same sentence as TCL1B in open-access papers:
TCL1B is named in the same sentence as 13 diseases in open-access papers, as found by Europe PMC text mining. Sharing a sentence is not in itself a finding about the gene and the disease. The quoted sentences say what the papers report.
leukemia (6 papers, 2005 to 2025). A malignant (clonal) hematologic disorder, involving hematopoietic stem cells and characterized by the presence of primitive or atypical myeloid or lymphoid cells in the bone marrow and the blood. "AKT1 and AKT2 both interact with all TCL1 family members like TCL1, MTCP1, and TCL1b in leukemia cells and as consequence the activity of both isoforms is increased in an unspecific manner." (PMID 31752925, 2019). "Targeting the TCL1B‐mediated AKT signaling could potentially be a novel therapeutic approach for the treatment of leukemia and lymphoma." (PMID 41163374, 2025). "It is interesting to detect the TCL6 in leukemia-specific MAEs, since it was recently reported that low TCL6 levels were associated with poor survival of B-cell ALL patient, through a link between TCL6, TCL1B, and the AKT1 pathway." (PMID 34722498, 2021).
lymphoma (3 papers, 2005 to 2025). A malignant (clonal) proliferation of B- lymphocytes or T- lymphocytes which involves the lymph nodes, bone marrow and/or extranodal sites. "TCL1B belongs to the TCL1 family of oncoproteins, plays a significant role in the development of leukemia and lymphoma." (PMID 41163374, 2025).
T-cell leukemia (3 papers, 2018 to 2025). A malignant disease of the T-lymphocytes in the bone marrow, thymus, and/or blood. "The pathogenesis of T-PLL involves rearrangement of the TCR, located on chromosome 14q) and juxtaposition with T-cell leukemia (TCL) genes, leading to the aberrant expression of TCL1A, TCL1B, or MTCP1 oncogenes in approximately 95% of cases." (PMID 41259500, 2025). "The most significant SNP marker at 14q32.13 (rs117410836) is located near an uncharacterized long non-coding RNA (lncRNA; LINC02318), GLRX5 (glutaredoxin 5), and members of the T-cell leukemia (TCL) gene family (TCL1A, TCL1B, and TCL6)." (PMID 30305637, 2018).
angiosarcoma (1 paper, 2013). A malignant tumor arising from the endothelial cells of the blood vessels. "The observation supported that TCL1b-mediated activation of Akt may underlie the malignant transformation of generation of angiosarcoma." (PMID 24042734, 2013). "Further, two independent lines of β-actin promoter-driven TCL1b-transgenic mice developed angiosarcoma on the intestinal tract." (PMID 24042734, 2013). "The observation supported the notion that TCL1b possibly has an active role in the pathological condition of angiosarcoma in humans." (PMID 24042734, 2013). "In this regard, we showed that 11 out of the 13 cases of human angiosarcoma showed positive result with anti-TCL1b and anti-phospho-Akt." (PMID 24042734, 2013). "As TCL1b expresses ubiquitously as was suggested by the housekeeping type of 5′-promoter sequences, we have created β-actin-driven TCL1b-transgenic mice, which resulted in angiosarcoma in the intestinal submucosal tissues." (PMID 24042734, 2013). "Given the highly positive immunostaining of TCL1b in human angiosarcoma and various human cancer tissues, it is plausible that TCL1b can serve as a putative molecular target for neoplastic diseases in general, in particular targeting angiosarcoma in humans." (PMID 24042734, 2013). "TCL1b showed potent oncogenicity both in vitro and in deregulated mice, which resulted in angiosarcoma of the intestinal tract." (PMID 24042734, 2013). "Consistently, human angiosarcoma samples and human cancer tissue array were positively stained with anti-TCL1b and anti-phospho-Akt antibodies." (PMID 24042734, 2013). "Using immunohistochemistry, 11 out of 13 human angiosarcoma samples were positively stained with both anti-TCL1b and anti-phospho-Akt antibodies." (PMID 24042734, 2013). "It is plausible that TCL1b possibly serves as a putative therapeutic target for angiosarcoma, a rare form of human neoplastic disease with poor prognosis." (PMID 24042734, 2013). "Moreover, as predicted by the inhibition of Akt kinase activity, ‘TCL1b-Akt-in' inhibited cellular proliferation of angiosarcoma or reticulosarcoma." (PMID 24042734, 2013). "Indeed, by using immunohistochemistry, 11 out of 13 cases of human angiosarcoma were stained positive with both anti-TCL1b and phospho-Akt antibodies." (PMID 24042734, 2013). "Furthermore, we showed that 11 out of the 13 cases of human angiosarcoma stained positive with both phospho-Akt and TCL1b using immunohistochemistry." (PMID 24042734, 2013). "Notably, ‘TCL1b-Akt-in' effectively inhibited the cellular proliferation of angiosarcoma." (PMID 24042734, 2013).
gastric cancer (1 paper, 2013). A primary or metastatic malignant neoplasm involving the stomach. "TCL1b was positively stained in 25 of 43 (58.1%) head and neck cancer types, 32 of 67 (47.8%) esophagus and gastric cancer types, 8 of 27 (29.7%) liver, bile duct and pancreas, and finally in 4 of 9 (44.4%) lung cancer types." (PMID 24042734, 2013).
myopia (1 paper, 2023). "Interestingly, locus rs56111147 was potentially associated with three indexes except for SD, and it was located in the gene TCL1B, which has been previously linked to myopia." (PMID 37658396, 2023).
Parkinson disease (1 paper, 2022). A progressive degenerative disorder of the central nervous system characterized by loss of dopamine producing neurons in the substantia nigra and the presence of Lewy bodies in the substantia nigra and locus coeruleus. "The TCL1B gene, which is predicted as one target of miR-3181, showed significant differential expression between Parkinson’s disease patients and NC." (PMID 35528544, 2022).
sarcoma (1 paper, 2013). A usually aggressive malignant neoplasm of the soft tissue or bone. "Functionally, ‘TCL1b-Akt-in' effectively inhibited the cellular proliferation of sarcoma cells." (PMID 24042734, 2013). "In sarcoma tissues positively stained by both anti-VEGFR2 (vascular endothelial growth factor receptor 2) and TCL1b by confocal microscopy." (PMID 24042734, 2013).
cancer (3 papers, 2013 to 2025). A tumor composed of atypical neoplastic, often pleomorphic cells that invade other tissues. "The pathway of KEGG mapping in cancer also exhibited highly similar gene-induction signatures with TCL1b, TCL1 or Myr-Akt." (PMID 24042734, 2013). "Consistently, in various cancer tissues, 69 out of 146 samples were positively stained with anti-TCL1b, out of which 46 were positively stained with anti-phospho-Akt antibodies." (PMID 24042734, 2013). "The observation together strongly supported that the protooncogene TCL1b is a novel molecular target with therapeutic potential for human cancer types in clinical settings." (PMID 24042734, 2013). "In this analysis, 69 cases out of 146 (47.3%) cancer tissue samples showed positive results with the TCL1b antibody." (PMID 24042734, 2013). "Notably, among the 69 cases of TCL1b-positive cancer tissues, 46 cases (67%) were stained positive simultaneously with the anti-phospho-Akt antibody." (PMID 24042734, 2013). "The observations together supported the notion that TCL1b, which activates Akt, possibly underlies various human cancer types of non-lymphoid lineages." (PMID 24042734, 2013). "Notably, immunohistochemistry of human cancer array showed 69 out of 146 human cancer derived from various tissue origins appeared positively stained with the anti-TCL1b antibody." (PMID 24042734, 2013). "Out of 327 total genes listed in the cancer pathway of KEGG, 16 genes were altered by TCL1b, 20 genes by Myr-Akt and 15 genes by TCL1." (PMID 24042734, 2013). "By integrating insights from transmembrane adaptor proteins, like TMEPAI, transcriptional regulators such as SALL4, oncoprotein coactivators similar to TCL1B, and cytokine signals akin to TGF‐β, we gain a more holistic understanding of how PI3K/AKT is hyperactivated in cancer." (PMID 41163374, 2025). "It is of note that in human cancer tissue arrays, positive staining of TCL1b appeared to show no obvious correlations with clinical stages of human cancer types." (PMID 24042734, 2013).
tumor (3 papers, 2013 to 2024). "Collectively, observation disclosed that TCL1b indeed functions as an Akt kinase co-activator, underlies neoplastic diseases in vivo and, therefore, possibly serves as a novel therapeutic target of human neoplastic diseases." (PMID 24042734, 2013). "In this study, we investigated whether and how TCL1b functions as an Akt kinase co-activator and exhibits oncogenic potency, both in vitro and in vivo, underlying various human neoplastic diseases." (PMID 24042734, 2013). "The current study disclosed TCL1b bears oncogenicity and hence serves as a novel therapeutic target for human neoplastic diseases." (PMID 24042734, 2013). "Furthermore, it is possible that suppression of TCL1b isoform could serve as a potential therapeutic target for various human neoplastic diseases." (PMID 24042734, 2013). "TCL1A was upregulated in a majority of PTCLs, whereas TCL1B was not significantly increased in any of the tested tumor subtypes." (PMID 38464090, 2024). "Therefore, it remains unclear whether TCL1b itself, independent of TCL1, bears oncogenicity, in vivo, underlying human neoplastic diseases." (PMID 24042734, 2013).
TCL1B also shares sentences with these, for which no sentence is quoted: head and neck cancer (1 paper); lung carcinoma (1); reticulosarcoma (1).